BCL2 (BCL2 apoptosis regulator)
Diseases named in the same sentence as BCL2 in open-access papers (continued):
Sharing a sentence is not in itself a finding about the gene and the disease.
tumor (continued). "Evaluating with Oncomine data, we found most target genes (BCL2, ERBB2/3, SIRT7, ETS1, Mcl-1, IL6R, and LIN28B) were significantly activated in HCC tumor tissues, consistent with miR-125b underexpression." (PMID 25861255, 2015). "Further, the co-expression of Bcl-2 with p-p38 correlated with low EFS scores and poor OS for the patient’s tumor with the ABC subtype." (PMID 26475474, 2015). "SFT cells are positive for CD34 in 90–95% of tumours, MIC2 in 70% of tumours and Bcl-2 in >80% of tumors." (PMID 25663869, 2015). "We employed a range of antibodies to characterize the immunophenotype of the tumor cells and found that the tumor cells were positive for CD34, CD99, bcl-2, and vimentin." (PMID 25688313, 2015). "Their target prediction and pathway analysis showed that miR-126 can regulate key molecules and critical pathways involved in ccRCC tumor development and progression, including the IGF1R, BCL2, HIF-1, VEGF, mTOR, and PI3K-Akt signaling pathways." (PMID 26416448, 2015). "NF-κB plays a critical role in the regulation of proteins involved in the cell survival (Bcl-2, XIAP), proliferation (cyclin-D1), invasion (MMP-9, RANKL), angiogenesis (VEGF), and inflammation (COX-2, TNF-α), all contribute to the tumor progression." (PMID 26487364, 2015). "miR-21 simultaneously regulates multiple programs that enhance cell proliferation, apoptosis and tumor invasiveness by targeting PTEN, RECK and Bcl-2 in GSQCLC." (PMID 25084400, 2014). "The data suggested that DB is capable to induce tumor specific growth inhibition in oral GNM and TSCCa cancer cells via Bax/Bcl-2-mediated intrinsic mitochondrial apoptotic pathway in time- and dose-dependent manners." (PMID 24972848, 2014). "MiR-21 functions as an oncogenic microRNA by targeting multiple tumor suppressor genes including PTEN, PDCD4, BCL-2, TPM1, and RECK, and its participation has been reported in many human cancers." (PMID 25428915, 2014). "Overexpression of CAM2KN1 in DU145 tumor tissues resulted in decreased ErbB2, AKT1, Bcl-2, NF-κB and AR mRNA levels and increased p21, Bax mRNA levels." (PMID 25003983, 2014). "Therefore, BCL-2 expression may also reflect lower degree of tumour differentiation." (PMID 25005788, 2014). "Kappa and lambda FLC expression showed significant negative correlations with tumor-relevant markers usually associated with favorable clinical outcome including the hormonal receptor markers for estrogen and progesterone and the apoptotic marker Bcl2 (p<0.001)." (PMID 24931643, 2014). "Molecular studies done on excised tumor (A549) tissue suggested that BBR in SD form resulted in a significant decrease in the survivin, Bcl-2, cyclin D1, MMP-9, HIF-1α, VEGF and CD31 expressions." (PMID 24614362, 2014). "The tumor tissues were harvested after treatment, and ACBP-L and Cisplatin treatment suppressed Bcl-2, and induced Bax, Caspase 3, and Caspase 8 molecules as detected by RT-PCR and immunohistochemistry." (PMID 24507386, 2014).
tumor (continued). "Finally, further investigation of the signaling mechanisms by which auranofin downregulates the expression of antiapoptotic proteins IKK-β and Bcl-2 that in turn contributes to tumor cell survival/growth may provide new cellular targets that can be exploited therapeutically." (PMID 25096914, 2014). "curcumin has been shown to suppress the expression of a variety of NF-κB regulated gene products involved in carcinogenesis and tumor growth including cyclin D1, VEGF, COX-2, c-myc, Bcl-2, ICAM-1 and MMP-9." (PMID 25866478, 2014). "Luminal A tumours tend to be low grade tumours that are characterised by over expression of ER-activating genes including LIV1, CCND1, FOXA1, XBP1, GATA3 and Bcl-2." (PMID 24392136, 2014). "We studied the series of 336 DLBCL, NOS tumor samples by IHC on the TMAs using antibodies for MYC, BCL2, BCL6 and Ki67." (PMID 25090026, 2014). "BCL-2 induction and p-STAT3 (Y705) activation were found within the residual tumor cells surviving the initial antitumor response to targeted therapies." (PMID 25364578, 2014). "Imidazotetrazine analogues of TMZ and the BH3 mimetic obatoclax are promising clinical candidates in drug resistant MB tumours expressing MGMT and BCL2 anti-apoptotic members respectively." (PMID 24887326, 2014). "Overexpression of GATA3 in normal hMEC cells resulted in downregulation of BCL2, DACH1 and THSD4, supporting a tumor suppressor function for GATA3 under normal conditions." (PMID 25410484, 2014). "Taking into account only the chromosomal bands harboring BCL2-, BCL6-, IGH- and MYC loci, translocations had been detected in 32/46 tumor samples by chromosome banding, while FISH analysis revealed breaks in 30/46 samples." (PMID 24733537, 2014). "To understand the role of LRPPRC in tumor development, previously we reported that LRPPRC forms a ternary complex with Beclin 1 and Bcl-2 to inhibit autophagy." (PMID 24722279, 2014). "Some tumor suppressors induce autophagy, for example, Beclin 1, UVRAG, PTEN and Bcl-2, while some oncogenic proteins like mTOR inhibit autophagy." (PMID 25121098, 2014). "Because miR-195 is involved in repression of cell cycle accelerators (CCND1, CCNE1, CDK4, CDK6, and E2F3) and anti-apoptotic factors (BCL2, BCL2L2, and BIRC5), miR-195 functions as a tumor suppressor miRNA in various types of human cancers." (PMID 25364765, 2014). "To further explore the mechanism of EESP’s anti-tumor activity, we performed RT-PCR and IHS analyses to respectively examine the mRNA and protein expression of Bcl-2, Bax, Cyclin D1, CDK4, VEGF-A and VEGFR-2 in CRC mice." (PMID 23800091, 2013). "Whilst all the spindle cells within the tumour expressed CD34, AR, ER, BCL2, and CD10, only those within the myofibroblastoma expressed desmin and only those within the lipomatous areas expressed S100." (PMID 24459597, 2013). "Immunohistochemistry showed that the tumor cells were diffusely positive for CD34, CD99, Bcl-2 and vimentin." (PMID 24179528, 2013). "Consequently, downregulation of the anti-apoptotic gene products BCL2/BCL-XL/XIAP via NF-κB inhibition may allow tumor cells to be sensitive to apoptosis induction by low doses of TMZ, as is the case for U251 showing strongly potentiated apoptosis despite being resistant to single treatments." (PMID 23533755, 2013). "Immunohistochemical studies show strong staining of the tumor cells with CD34, Bcl-2, CD99, and vimentin." (PMID 23662242, 2013). "Further, this study also identifies the potential of the extracted polyphenols on major tumor progression molecular targets including NFκB, EGFR, kRAS, STAT3, VEGF, AKT, TERT, FGFA, BCl2 and PDGFA." (PMID 23613993, 2013).
tumor (continued). "Using tumor cells other than CaP, we also showed that regulation of TCF4-mediated BCL2 by BMI1 is universal." (PMID 23671559, 2013). "The main tumour spindle-shaped cells as well as those entrapped within the fat lobules were positive for CD34, BCL2, ER, AR, and CD10 (weak)." (PMID 24459597, 2013). "Immunohistochemically, these spindle tumor cells showed diffuse CD34 and Bcl-2 positive reactivity, S-100 protein and HMB45 were negative, Masson colouration disclosed lots of collagenous fiber." (PMID 24294990, 2013). "Increased expression of COX-2 was observed in the tumor cells after irradiation, and COX-2 expression decreased in relation with Bcl-2 expression." (PMID 23533613, 2013). "The protein levels of Cyclin D1, Pro-Caspase-3, Bcl-2, MMP2 and MMP9 in tumor extracts were examined by western blot." (PMID 23874680, 2013). "Accordingly, over-expression of the anti-apoptotic gene Bcl2 inhibits DEN-induced liver carcinogenesis, primarily due to attenuation of tumor initiation." (PMID 24339898, 2013). "The tumor cells in the present case were positive for CK, CAM5.2, SMA, CK19, CR and CD34, while the markers for bcl-2, PLAP, CD117, S-100, CD20, CD79a, CD45RO, CD15, CD30 were negative." (PMID 23946800, 2013). "miR targeting of oncogene mRNA expression can act in its nature as a tumor suppressor; for example, miR-15a, which is downregulated in CLL, prostate cancer, and pituitary adenomas, targets anti-apoptotic BCL2." (PMID 24029073, 2013). "The tumor cells expressed CD20 (7 of 7), CD79a (6 of 6), BCL2 (5 of 7), BCL6 (4 of 7) and MUM1 (5 of 7)." (PMID 23915571, 2013). "Bcl-2, however, is a known NFκB target gene and its expression is decreased with PDTC treatment in both non-tumor bearing epidermis and tumors." (PMID 22761871, 2012). "Bax, Bcl-2 and Bcl-XL protein expression was quantified using fluorescent IHC and AQUA technology in normal oral cavity squamous epithelium (OCSE) and OSCC tumour samples." (PMID 22852863, 2012). "In the present study, we evaluated the expression of Bcl-2, Bcl-XL and Bax using the AQUA technique in 69 OSCC tumour samples and compared these results to normal oral cavity squamous epithelium (OCSE)." (PMID 22852863, 2012). "In our work, it was found that DA down-regulated the Bcl-2 and Bcl-xl expression, while concomitantly up-regulating the Bax and Bid expression, and the ratio of Bax/Bcl-2 increased correspondingly, which could be an important mechanism contributing to the induction of tumor cell apoptosis by DA." (PMID 22942759, 2012). "BCL2, Bcl-xL, XIAP and survivin are the most important antiapoptotic members of these two families and are frequently upregulated in human tumours including BCa." (PMID 22797576, 2012). "Previous reports indicate that the NIX/BNIP3L gene acts as a pro-apoptotic factor by interacting with BCL2 and BCL-XL, playing an important role in hypoxia-dependent cell death and acting as a tumor suppressor." (PMID 22984526, 2012). "These tumor suppressive effects of miR-34a are mediated by changes in a number of target mRNAs including MYCN, CDK4, cyclin D1, SIRT1 and Bcl-2." (PMID 22629428, 2012). "Mice receiving Bcl-2 knockdown mutants, either BEAS-Cr or H460, showed a substantial reduction in tumor volume as compared to their respective controls." (PMID 22666341, 2012). "In AML, miR-29 expression is negatively correlated with MCL-1 mRNA, while in HCC BCL-2 and MCL-1 were both direct targets of miR-29; both of these findings support the theory that miR-29 functions as a tumor suppressor in cancer by promoting apoptosis." (PMID 23335942, 2012).
tumor (continued). "In tumor cells with type II TRAIL-induced apoptosis, cell death can be blocked by the overexpression of antiapoptotic Bcl-2 proteins, such as Bcl-2 and Bcl-xL." (PMID 22577581, 2012). "We also stained tumor sections with antibodies specific to phosphorylated 4E-BP1 and oncogenic and growth promoting proteins such as cyclin D1, cyclin E, c-Myc, Bcl-2, and VEGF." (PMID 22935625, 2012). "The two miRNAs that were highly upregulated in sera from patients with oral HRLs (miR-16 and let-7b) have been reported to act as tumor suppressors (downregulating oncogenes like RAS, BCL2) and are known to be downregulated in many cancer types." (PMID 23342275, 2012). "Zinc is an inhibitor of HIF-1α in human cancers that represses important genes involved in tumor progression, such as VEGF, MDR1 and Bcl2." (PMID 23284967, 2012). "The morphological changes in cell tumor were observed through the immunohistochemical method using an electron microscope to detect the expressions of MRP3 and Bcl-2 and to investigate the molecular mechanisms of Anip973/NVB cells." (PMID 22429577, 2012). "Tumour specimens from these patients were graded histopathologically, and immunnohistochemistry for Ki-67, CD31, androgen receptor (AR), Her-2/neu, Bcl-2, and PTEN were performed." (PMID 23077456, 2012). "Further, overexpression of BCL-2 or BCL-XL in these mice or in transplanted bone marrow cells accelerates MYC-driven tumor development, suggesting that BCL-2 and BCL-XL act in synergy with MYC in tumorigenesis." (PMID 22393362, 2012). "Our detailed studies of the kinetics of tumor development showed that overexpression of MYC, either alone or together with BCL-XL or BCL-2, rapidly resulted in blast transformation of various hematopoietic cell types, including myeloid and lymphoid cells." (PMID 22393362, 2012). "Immunohistochemical staining (SP) shows the positive expressions of Bcl-2 and MRP3 proteins in Anip973/NVB transplantation tumor, which were observed to be higher than those in the Anip973 transplantation tumor." (PMID 22429577, 2012). "STAT3 activation can upregulate the expression of anti-apoptotic proteins (Bcl-2, Mcl-1 and Bcl-x), proliferation related proteins (cyclin D1 and c-Myc) and angiogenesis promoting factors (VEGF) to prevent tumor cells from apoptosis." (PMID 23554768, 2012). "We analysed changes in tumour cell density, nuclear size, and binding of TS1, Ki67, and Bcl-2 at different time points." (PMID 22214480, 2011). "Tumor cells can induce drug resistance through inducing drug efflux pump (p-glycoprotein or MDR1), by up-regulation of anti-apoptotic genes (Bcl-2, Bcl-xl) or by other mechanisms." (PMID 21957481, 2011). "The study therefore suggested BCL-2 as a possible novel cellular target of miR-24-2 and confirmed H2AX regulation by miR-24-2 in proliferating cell lines and in tumor samples." (PMID 21463514, 2011). "The level of SIRT1 was low, while high amounts of BCL2, MDM2 and PTBP1 were noted in both types of tumours." (PMID 21655185, 2011). "Bcl-2 and bax gene were induced to participate in regulation for the apoptosis of VX2 tumor cell by ionizing radiation from 32P-CP-PLLA microparticles, so that the tumor growth was inhibited." (PMID 21219823, 2011). "For Bcl-2, 140 cases, of the possible 184 cases present on the whole TMA, had sufficient stained tumour tissue to evaluate staining at the level of the TMA used." (PMID 21063403, 2010). "Because anti-apoptotic Bcl-2 is highly expressed in various human cancers, this feature of HNTMB increases its potential as an alternative anti-tumor drug." (PMID 20184758, 2010). "BCL2, ER, progesterone receptor (PR) and human epidermal growth factor receptor 2 (HER2) levels were determined in all tumours." (PMID 20664598, 2010).
tumor (continued). "Many proteins that are crucial for tumor cell proliferation and survival have been found to be regulated by STAT3; these include Bcl-2, Bcl-XL, cyclin D1/D2 and IL-6, which are considered to contribute to the anoikis resistance-inducing property of STAT3." (PMID 20507639, 2010). "XIAP, Survivin and Bcl-2 met all these criteria and are characterized as upregulated in PDAC cell lines as well as native tumor tissue." (PMID 20646298, 2010). "In this study, we used the siRNAs targeted to mdr1b, mdr1a, and bcl-2 mRNAs to reverse the MDR of tumors and increase tumor sensitivity to chemotherapeutics." (PMID 20470373, 2010). "In the present study, we found that stromal Bcl-2 staining decreased with malignant progression and the intensity of stromal Bcl-2 expression was inversely related to tumor grade, possibly suggesting that alterations in stromal components might promote tumor progression." (PMID 19852858, 2009). "Other mechanisms elaborated by tumor cells to develop cell death resistance include aberrant expression of anti-apoptotic molecules such as c-FLIP, Bcl-2, Bcl-xL, survivin and Livin." (PMID 19232089, 2009). "Ki67, Mcm3, and ssDNA expression was confined to tumour cell nuclei, and Bax, Bcl-2, Grp78, and VEGF immunoreactivity to the tumour cell cytoplasm." (PMID 19491899, 2009). "Immunohistochemistry analysis for BCL2 and BCL6 was performed on tumor tissue from 24 and 26 DLBCL patients, respectively, in our series." (PMID 20016842, 2009). "BCL2, MYC, CCND2, BCL6 and LMO2 expression was studied in tumor tissue from 12 DLBCL patients of our series using real-time PCR." (PMID 20016842, 2009). "The tumor foci and volumes of CD133+ treated by DBH+IR alone or DBH+IR combined with BCL-2 siRNA were significantly decreased compared to those of CD133+ and only IR-treated CD133+ (p<0.01)." (PMID 18509505, 2008). "BH3 mimetics such as ABT-737 bind with high affinity to BCL-2, BCL-xL, and BCL-w, and kill certain tumor cells when used alone or in combination with chemotherapeutic drugs or γ-irradiation." (PMID 17973573, 2007). "The effect was assessed 4 weeks later by evaluating the tumours for mitosis, necrosis, apoptosis, and expressions of IGFBP-4, Bcl-2 and Bax proteins." (PMID 17988381, 2007). "Our findings therefore support the hypothesis that Bcl-2 expression in the target U937 and A02 cells suppressed the proapoptotic effects of antitumour immune cells, and that inhibition of Bcl-2 can remove this suppression and allow apoptosis of the tumour cells to proceed." (PMID 17311012, 2007). "Western blotting was used to evaluate changes in expression of β-tubulin, HER2, p-ERK, p-AKT, p27, BCL2, AR, HSP90 and HSP70 induced by treatment with docetaxel alone or the trastuzumab plus docetaxel combination in HID28 tumours, a very high responder." (PMID 17211467, 2007). "The higher expression of IGF1, BCL2, and CCND1 in the BEST prognosis group was unanticipated, as these genes are commonly considered to be tumor- promoting genes." (PMID 17206280, 2007). "In the intrinsic route, increased levels of the antiapoptotic protein Bcl-2 in primary NBs correlate with unfavourable histology according to Shimada and with MYCN amplification, and seem to promote tumour cell survival." (PMID 16755292, 2006). "Thus, Bcl-2-positive tumours may be slow growing and so possess less malignant potential." (PMID 14710230, 2004).